HTRA2 (HtrA serine peptidase 2)
Diseases named in the same sentence as HTRA2 in open-access papers (continued):
Sharing a sentence is not in itself a finding about the gene and the disease.
essential tremor (5 papers, 2016 to 2020). A relatively common disorder characterized by a fairly specific pattern of tremors which are most prominent in the upper extremities and neck, inducing titubations of the head. "Recently, a research by Gulsuner and colleagues examining a six-generation family segregating ET and ET coexisting with PD revealed that HTRA2 p.G399S is responsible for hereditary essential tremor and homozygotes for this allele develop Parkinson's disease." (PMID 28243480, 2017). "The G399S mutation was subsequently found to co-segregate with PD and essential tremor in a large family with multiple affected individuals of Turkish descent, providing further genetic evidence for the pathogenic role of G399S mutant Omi/HtrA2." (PMID 29372317, 2018). "To validate the condition in Chinese familial essential tremor (FET) and familial Parkinson's disease (FPD) patients, we performed a Sanger sequencing of eight exons and exon-intron boundaries of HTRA2 instead of just one variant (p.G399S)." (PMID 28243480, 2017).
hepatocellular carcinoma (5 papers, 2019 to 2024). A malignant tumor that arises from hepatocytes. "Furthermore, HTRA2 has been implicated in the suppression of hepatocellular carcinoma cell proliferation through its interaction with astrocystin." (PMID 39600313, 2024). "The upregulation of HTRA2 within the tumor microenvironment of hepatocellular carcinoma warrants further exploration, as supported by analysis of the GEO dataset and examination of clinical tissue specimens in our investigation." (PMID 39600313, 2024). "The role of HTRA2 in inducing apoptosis in hepatocellular carcinoma is contingent upon its expression levels." (PMID 39600313, 2024). "Prior study showed that hypoxia-inducible factor (HIF)-1alpha inhibits Omi/HtrA2 expression and suppresses hepatocellular carcinoma cell apoptosis." (PMID 31627188, 2019). "Besides, HtrA2 has also been reported to participate in the suppression of hepatocellular carcinoma cell growth by staurosporine." (PMID 36704205, 2023). "In addition, the occurrence of hepatocellular carcinoma cell apoptosis is highly dependent on HtrA2 expression." (PMID 36704205, 2023). "However, the role of HtrA2 in hepatocellular carcinoma (HCC) remains unclear." (PMID 36704205, 2023).
sarcopenia (5 papers, 2021 to 2024). Progressive decline in muscle mass due to aging which results in decreased functional capacity of muscles. "To further investigate the cause of sarcopenia due to deficiency of HtrA2 activity, we used UCF101 to inhibit HtrA2 enzymatic activity during myogenic differentiation of C2C12 cells." (PMID 36233059, 2022). "Mice deficient in HtrA2 protease activity show a distinct phenotype of sarcopenia." (PMID 36233059, 2022). "In addition to prototypical cofactors of mitochondrial biogenesis, Zhou and colleagues demonstrated that deficiency of high-temperature requirement protein A2 (HtrA2/Omi) protease is involved in the development of sarcopenia by negatively regulating mitochondrial biogenesis." (PMID 34881083, 2021). "Previous studies have mostly focused on the potential regulation of apoptosis by HtrA2/Omi proteins in neurodegenerative diseases, sarcopenia, and tumors." (PMID 38338855, 2024). "HtrA2 mnd2 (-/-) mice manifested low muscle mass, poor physical function and sarcopenia phenotypes." (PMID 34881083, 2021). "Conversely, knocking out HtrA2/Omi (a protein regulating IMS protein homeostasis) in vitro leads to IMS protein imbalance, activating UPRmt and ultimately inducing sarcopenia." (PMID 39571164, 2024). "Absence of HTRA2/OMI protease activity induced denervation-independent skeletal muscle degeneration with sarcopenia phenotypes in mice." (PMID 37152937, 2023). "Intriguingly, HtrA2 apparently regulates mitochondrial biogenesis in sarcopenia via the differential expression of Nrf-1/2, but not PGC-1α." (PMID 34881083, 2021).
gastric cancer (4 papers, 2021 to 2024). A primary or metastatic malignant neoplasm involving the stomach. "Recent research has demonstrated the possibilities of plasma HTRA2 as a clinical diagnostic biomarker for gastric cancer." (PMID 39600313, 2024). "High‐throughput sequencing screened HTRA2 positively correlated with gastric cancer malignant cell phenotype." (PMID 34708890, 2021). "In our study, we have observed that over‐expression of HTRA2 significantly promote cell proliferation while the knocking down of HTRA2 decrease cell variability in gastric carcinoma cell lines." (PMID 34708890, 2021). "In conclusion, HTRA2 promotes malignant phenotype of gastric cancer." (PMID 34708890, 2021).
glaucoma (4 papers, 2019 to 2024). Increased pressure in the eyeball due to obstruction of the outflow of aqueous humor. "Considering the beneficial effects of the CDR-induced HTRA2 protease inhibition on RGCs ex vivo, this might also indicate a pathogenic role of these processes in the pathogenesis of glaucoma; i.a. by hyperactivation." (PMID 34440217, 2021). "Nevertheless, how exactly the synthetic CDR1 peptide influences the biological functions of HTRA2 has to be addressed in future studies and will aid to unravel the complex neuroprotective mechanisms on RGCs in glaucoma." (PMID 34445599, 2021). "Based on these results, we could suggest a possible involvement of HTRA2 in the apoptotic process related to glaucoma." (PMID 38727311, 2024). "In accordance with this, our group verified in a recent study that the synthetic peptide ASGYTFTNYGLSWVR, encoding the hypervariable sequence part of an antibody, showed a high affinity for the target protein HTRA2 and triggered neuroprotection in an in vitro organ culture model for glaucoma." (PMID 34440217, 2021). "These important findings lead to the assumption that HTRA2 might represent a key player in neurodegenerative diseases such as glaucoma, and may serve as a potential therapeutic target in the future." (PMID 34440217, 2021). "Moreover, our results support the mitochondrial serine protease HTRA2 as a key player in the pathogenesis of glaucoma, which should receive particular focus in future glaucoma research projects." (PMID 31443184, 2019). "However, in a recent study by our group, it was demonstrated that the synthetic CDR1 peptide ASGYTFTNYGLSWVR induced neuroprotection on retinal ganglion cells (RGC) in an in vitro glaucoma model and possessed a high affinity for the target protein HTRA2, verified by immunoprecipitation experiments." (PMID 34440217, 2021). "Thereby, the exogenous application of synthetic CDR1 peptide or protease inhibitor UCF-101 (blocking the catalytic domain of HTRA2) highly influenced the HTRA2-specific interactome in the retina and might highlight the importance of these signaling pathways in the pathogenesis of glaucoma." (PMID 34445599, 2021). "However, for glaucoma, the exact role of HTRA2 is still unknown and represents a very attractive target for future glaucoma-related study designs." (PMID 31443184, 2019). "Accordingly, Rho-Kinase (ROCK) inhibitors are attractive treatment options in glaucoma therapy because of their multifunctional IOP-lowering effects, and might indicate the regulatory function of HTRA2 in this important pathway mechanism." (PMID 34440217, 2021).
ovarian carcinoma (4 papers, 2012 to 2023). A malignant neoplasm originating from the surface ovarian epithelium. "Cisplatin induces XIAP content decrease and cytosolic HtrA2/Omi level increase in cisplatin-sensitive ovarian cancer cells." (PMID 35582023, 2021). "However, the expression of HtrA2 was found to be very low, which predicted poor outcomes in non-small-cell lung cancer and ovarian cancer." (PMID 36704205, 2023). "Furthermore, ovarian cancer cells with higher levels of HtrA2 are more sensitive to cisplatin, and the knockdown of HTRA2 in these cells drastically increases cisplatin resistance and increases cell invasiveness." (PMID 34639128, 2021).
cognitive deficits (3 papers, 2017 to 2025). "Among the 20 DEPs identified, HTRA2 has been linked to AD, one of the most common cognitive disorders." (PMID 39794315, 2025). "Finally, we showed that lentivirus-mediated HTRA2 overexpression in the hippocampus rescued PP2B reduction, alleviated tau hyperphosphorylation, and partially attenuated synaptic plasticity and cognitive deficits in the PS19 tauopathy model mice." (PMID 39794315, 2025).
Dystonia (3 papers, 2017 to 2025). An abnormally increased muscular tone that causes fixed abnormal postures. "Among the most significant genetic links are the genes LINGO1, HTRA2, and DNAJC13, which have also been implicated in dystonia." (PMID 40731814, 2025). "HTRA2 variants represent a novel and significant cause of rapidly progressing, neonatal onset mitochondrial disease associated with 3-MGA-uria, hypotonia, dystonia, seizures and cardio-respiratory difficulties." (PMID 27696117, 2017). "Therefore, while LINGO1, HTRA2, and DNAJC13 remain important candidates linking ET, PD, and dystonia, definitive evidence supporting their direct contribution to PD risk is still lacking and requires further investigation." (PMID 40731814, 2025).
ischemia (3 papers, 2019 to 2022). A hypoperfusion of the BLOOD through an organ or tissue caused by a PATHOLOGIC CONSTRICTION or obstruction of its BLOOD VESSELS, or an absence of BLOOD CIRCULATION. "Inhibition of HTRA2 activity, particularly the catalytic protein domain, prevented myocardial dysfunction and inflammation-mediated tissue damaging events after ischemia/reperfusion injury in rat hearts in vivo." (PMID 31443184, 2019). "In addition, processed HTRA2 released into the cytosol after ischemia contributes to neuronal injury via inhibition of XIAP." (PMID 34708890, 2021). "In a brain ischemia rats model, the activated HtrA2/Omi gets translocated from mitochondria to the cytosol, which induces neuronal death, whereas its inhibition by a specific inhibitor, ucf-101, attenuated ischemia-induced activation of caspase-8 and caspase-3." (PMID 36306288, 2022).
liver fibrosis (3 papers, 2019 to 2024). "In this study, we demonstrated that mitochondrial dysfunction in hepatocytes is closely linked to hepatic fibrosis, and HtrA2/Omi might play a critical role in preventing of hepatic fibrogenesis through regulating mitochondrial homeostasis." (PMID 31547195, 2019). "Moreover, we found that motor neuron degeneration 2-mutant mice harboring the missense mutation Ser276Cys in the protease domain of HtrA2/Omi displayed altered mitochondrial morphology and function, which increased oxidative stress and promoted liver fibrosis." (PMID 31547195, 2019). "Restoration of HtrA2/Omi expression rescued CCl4-induced hepatic fibrosis in hepatocytes and reversed mitochondrial dysfunction (e.g., excessive ROS production)." (PMID 38338855, 2024). "It has also been demonstrated that restoration of HtrA2/Omi expression can rescue CCl4-induced liver fibrosis and reverse mitochondrial dysfunction in hepatocyte." (PMID 35449197, 2022). "The overexpression of HtrA2/Omi in the liver protects against CCl4 induced liver fibrosis through modulating mitochondrial homeostasis in hepatocytes." (PMID 35449197, 2022). "To further confirm the protective role of HtrA2/Omi, we examined the effects of the hydrodynamic gene delivery of pFLAG-HtrA2/Omi in the CCl4-induced liver fibrosis model." (PMID 31547195, 2019). "We attempted to identify and characterize the role of the mitochondrial serine protease HtrA2/Omi in improving mitochondrial damage during the progression of hepatic fibrosis." (PMID 31547195, 2019). "By hydrodynamics-based gene transfer, the overexpression of HtrA2/Omi leads to antifibrotic effects in CCl4-induced liver fibrosis mice model through decreasing collagen accumulation and enhancing anti-oxidative activity by modulating mitochondrial homeostasis in the liver." (PMID 31547195, 2019). "Given that both ROS and mitochondrial dysfunction contribute to liver fibrogenesis and that hepatocyte mtDNA can exacerbate HSC activation, we hypothesized that HtrA2/Omi plays a pivotal role in liver fibrosis by modulating mitochondrial homeostasis." (PMID 31547195, 2019). "Taken together, these data suggested that HtrA2/Omi has an important role in maintaining mitochondrial homeostasis that might decrease vulnerability to liver injury and the development of liver fibrosis." (PMID 31547195, 2019). "In addition, we demonstrate that downregulation of HtrA2/Omi expression in CCl4-induced liver fibrosis has a major role in modulating mitochondrial function and ROS generation in vivo and in vitro." (PMID 31547195, 2019). "Therefore, we observed that, by protecting the mitochondria, HtrA2/Omi could restore mitochondrial structure and mitochondrial function, and subsequent play a pathophysiological role in the liver fibrogenesis in CCl4-induced liver fibrosis model." (PMID 31547195, 2019).
rheumatoid arthritis (3 papers, 2017 to 2024). A chronic, systemic autoimmune disorder characterized by inflammation in the synovial membranes and articular surfaces. "We found that the concentration of HtrA2 was elevated in rheumatoid arthritis (RA) synovial fluid (SF) than in osteoarthritis (OA) SF, and its concentrations were correlated with the number of immune cells in the RA SF." (PMID 37287073, 2023).
Sepsis (3 papers, 2019 to 2022). Sepsis is defined as life-threatening organ dysfunction caused by a dysregulated host response to infection. "Anyhow, this suggests that Omi/HtrA2 protease associated cell apoptosis may participate in sepsis induced BBB dysfunction and septic encephalopathy." (PMID 30853894, 2019). "Our previous study indicated pre-treatment with UCF-101, a specific inhibitor of Omi/HtrA2, could significantly reduce neuronal apoptosis and attenuate sepsis-induced cognitive dysfunction." (PMID 30853894, 2019). "The present study was aimed to manifest whether inhibition of Omi/HtrA2 by RNA interference or UCF-101 treatment could improve BBB disruption induced by sepsis in vitro; if so, to probe the mechanisms by which Omi/HtrA2 induces BBB dysfunction and septic encephalopathy." (PMID 30853894, 2019). "Omi/high-temperature requirement serine protease A2 (HtrA2), a proapoptotic serine protease mainly found in and released from mitochondria, is found to be involved in the development of BBB dysfunction and SAE induced by sepsis through a caspase-dependent mitochondrial pathway." (PMID 34804998, 2021). "We confirmed that abrogation of Omi/HtrA2 by UCF-101 or Omi/HtrA2 shRNA in hCMEC/D3 monolayers could not significantly improve oxidative stress induced by sepsis in vitro." (PMID 30853894, 2019). "But, the molecular mechanism has not been studied and it has also not demonstrated whether suppression of Omi/HtrA2 expression level can improve BBB disruption induced by sepsis." (PMID 30853894, 2019).
3-methylglutaconic aciduria (2 papers, 2017 to 2024). A group of five inherited disorders caused by mutations in the AUH, DNAJC19, OPA3, and TAZ genes. "Biallelic variants in HTRA2 cause 3-methylglutaconic aciduria, type VIII (MGCA8), an extremely rare autosomal recessive disorder with fewer than ten families reported to date." (PMID 38304066, 2024).
atherosclerosis (2 papers, 2013 to 2017). A disease characterized by the build-up of fatty material and calcium deposition in the arterial wall resulting in partial or complete occlusion of the arterial lumen. "Hence, down-regulation of Omi/HtrA2 by siRNA may contribute to the positive effect of shear stress on endothelial cells by additionally stopping cells from entering apoptosis and thus prevent atherosclerosis." (PMID 24276320, 2013).
colitis (2 papers, 2019 to 2026). Inflammation of the colon. "In conclusion, our findings establish that 5-OH-TMT mitigates colitis through a newly identified mechanism involving direct HTRA2 inhibition." (PMID 41927825, 2026). "Our findings highlight the importance of HtrA2 in regulating colitis by modulation of necroptosis and suggest HtrA2 as an attractive target for anti-colitis treatment." (PMID 31019191, 2019). "UCF-101, a specific serine protease inhibitor of HtrA2, significantly alleviated DSS-induced colitis as indicated by prevention of body weight loss and decreased mortality." (PMID 31019191, 2019). "For the specific role of HtrA2 in necroptotic regulation and the relativity in DSS-induced colitis, the epithelial-specific HtrA2-knockout mice are needed for further investigation." (PMID 31019191, 2019). "Inhibiting the protease function of HtrA2 by treatment with UCF-101 ameliorated DSS-induced colitis in vivo." (PMID 31019191, 2019). "Our study raises the possibility of HtrA2 as a potential therapeutic target for anti-colitis treatment." (PMID 31019191, 2019). "Taken together, we discover HtrA2 as a positive regulator of necroptosis and colitis by degrading RIPK1 and our results suggest UCF-101 as a potential candidate for anti-colitis therapy in the future." (PMID 31019191, 2019). "Taken together, these results imply that the protease function of HtrA2 may play an important role in DSS-induced colonic inflammation." (PMID 31019191, 2019). "Further study is needed to determine whether the downregulation of HtrA2 is the cause of colitis development or whether the negative feedback protective mechanism is initiated by the colon tissue." (PMID 31019191, 2019). "Taken together, these results imply that inhibition of HtrA2 prevents DSS-induced colitis in mice, suggesting that downregulation of HtrA2 is a protective mechanism utilized by the host in the context of colitis." (PMID 31019191, 2019). "Our findings indicate HtrA2 downregulation as a protective mechanism to suppress necroptosis of colonic epithelial cells and to maintain colon barrier function in DSS-induced colitis." (PMID 31019191, 2019). "We speculate that HtrA2 may not be involved in colitis-associated apoptosis." (PMID 31019191, 2019). "Our data suggested that activation of HtrA2 contributed to DSS-induced colitis by promoting necroptosis but not apoptosis." (PMID 31019191, 2019). "Although UCF-101 inhibited necroptosis and ameliorated colitis in vivo, which is consistent with the pro-necroptosis activity of HtrA2 in vitro, we can not preclude the nonspecific effect of UCF-101 in vivo." (PMID 31019191, 2019). "Therefore, HtrA2 promotes necroptosis in a serine protease dependent manner and leads to epithelial damage of the colon in DSS-induced colitis." (PMID 31019191, 2019). "Since HtrA2 is downregulated in colitis and returned to normal level in UCF-101 treated mice, we propose that downregulation of HtrA2 is a protective mechanism to suppress necroptosis of colonic epithelial cells and to maintain colon barrier function in DSS-induced colitis." (PMID 31019191, 2019). "Since TNF-α is increased in colitis and endogenous HtrA2 is able to mediate necroptosis, necroptosis can still happen even when HtrA2 is not increased during DSS treatment." (PMID 31019191, 2019).